CDK19 (cyclin dependent kinase 19)
Diseases named in the same sentence as CDK19 in open-access papers (continued):
Sharing a sentence is not in itself a finding about the gene and the disease.
ovarian carcinoma (4 papers, 2022 to 2024). A malignant neoplasm originating from the surface ovarian epithelium. "CD24-miR-130a/301a-CDK19 signaling axis was associated with CSC-associated phenotypes in ovarian cancer cells." (PMID 38360723, 2024). "This study showed the relationship between CD24-regulated miRNAs and CSC phenotype acquisition in ovarian cancer and how CD24 contributes to CSC phenotype acquisition in ovarian cancer via miR-130a and 301a-dependent downregulation of CDK19." (PMID 38360723, 2024). "According to our results, CD24 expression increased G0/G1 phase cell population in ovarian cancer, which seemed to be mediated by decreased CDK19 expression and RNA synthesis." (PMID 38360723, 2024). "miR-130a and 301a were positively correlated in expression with CD24 in ovarian cancer patient tissues and negatively correlated with CDK19." (PMID 38360723, 2024). "It was recently shown that EVO decreases the expression of NEAT1 and CDK19, but increases miR-152 expression in ovarian cancer cells." (PMID 37046995, 2023). "Therefore, the expression of CD24, miR-130a, miR-301a, and CDK19 was analyzed with 53 cases of ovarian cancer patient tissues." (PMID 38360723, 2024). "The components of the CD24-miR-130a/301a-CDK19 signaling axis may be correlated with the poor prognosis of ovarian cancer patients." (PMID 38360723, 2024). "CD24-miR-130a/301a-CDK19 signaling axis could be a prognostic marker for or a potential therapeutic target against ovarian cancer recurrence." (PMID 38360723, 2024). "Our results suggest that the CD24-miR-130a/301a-CDK19 signaling axis could be a prognostic marker for or a potential therapeutic target against ovarian cancer recurrence." (PMID 38360723, 2024). "Therefore, studying the role of CDK19 in OC will help us to further understand the molecular mechanism of ovarian cancer development and provide new ideas for judging prognosis and treatment." (PMID 35451651, 2022). "Furthermore, EVO attenuates ovarian cancer cell progression via the NAET1/miR-152-3p/CDK19 axis." (PMID 37046995, 2023). "The role of CDK19 in tumorigenesis is rare, and its role in ovarian cancer has not been reported." (PMID 35451651, 2022).
microcephaly (3 papers, 2018 to 2019). A congenital or acquired developmental disorder in which the circumference of the head is smaller than normal for the person's age and sex. "In addition to the MED12 subunit, a disruption of CDK19 was reported in a patient with ID, microcephaly and congenital retinal folds." (PMID 29740699, 2018).
osteosarcoma (3 papers, 2017 to 2018). A usually aggressive malignant bone-forming mesenchymal neoplasm, predominantly affecting adolescents and young adults. "SJSA cells, an osteosarcoma cell line, contain CDK19, but the CDK8 protein is almost undetectable." (PMID 28416637, 2017). "A subset of osteosarcomas contain deletions in the 6q16-6q23 chromosomal region, which contains both CCNC and CDK19." (PMID 28416637, 2017). "Because the cyclin C (CCNC) gene is often deleted in malignancies such as acute lymphoblastic leukemia and osteosarcoma, CCNC and CDK19 may function as tumor suppressors." (PMID 28885545, 2017). "In osteosarcoma cells that do not express CDK8, knockdown of CDK19 resulted in reduced proliferation, accompanied by reduced mitotic gene expression." (PMID 30693281, 2018).
breast invasive ductal carcinoma (2 papers, 2019 to 2021). "CDK19 was increased in invasive ductal breast carcinoma (fold change = 1.682) in TCGA." (PMID 33686962, 2021).
cancers of the colon (2 papers, 2019 to 2025). "The Mediator kinase CDK8 and its paralog CDK19, together with their binding partner Cyclin C (CCNC), have been implicated through experimental studies in several malignancies, including cancers of the colon, breast, prostate, pancreas, melanoma, and leukemias." (PMID 31382571, 2019). "In contrast to the single knockouts,double knockout clones were completely unresponsive to CCT251921 treatment(T/C: 113 ± 10%, p < 0.005), demonstrating that inhibitionof both CDK8 and CDK19 is required to slow or arrest growth in theSW620 colon cancer xenograft model." (PMID 40601435, 2025). "Other cancers with a relatively high frequency of gene amplification included GI cancers, among which colon cancers, in particular, showed a unique specificity of gene amplification for CDK8 over CDK19, in agreement with the original report." (PMID 31382571, 2019). "Among the GI tract cancers, CDK8 was amplified much more frequently than CDK19 or CCNC, with no amplification of CDK19 or CCNC found in colon cancers (not shown)." (PMID 31382571, 2019).
developmental and epileptic encephalopathy (2 papers, 2021 to 2023). An epilepsy associated with developmental impairment that may be due to either the underlying etiology or the superimposed epileptic activity, or both. "Recently, missense variants in CDK19 have been shown to cause developmental and epileptic encephalopathy (MIM:618916), though partial gene deletions have been found in healthy individuals suggesting that haploinsufficiency of CDK19 may not be clinically relevant." (PMID 34512724, 2021).
Epileptic encephalopathy (2 papers, 2023 to 2024). A condition in which epileptiform abnormalities are believed to contribute to the progressive disturbance in cerebral function. "De novo variants in CDK19 are associated with a syndrome involving intellectual disability and epileptic encephalopathy." (PMID 39590469, 2024).
gastric cancer (2 papers, 2021 to 2023). A primary or metastatic malignant neoplasm involving the stomach. "Isochorismatase domain-containing 1 (ISOC1) is upregulated in gastric cancer, where it functions to activate and upregulate CDK19 in order to induce proliferation of gastric cancer cells and increase tumor size." (PMID 36769170, 2023).
head and neck squamous cell carcinoma (2 papers, 2020 to 2021). A squamous cell carcinoma that arises from any of the following anatomic sites: lip and oral cavity, nasal cavity, paranasal sinuses, pharynx, larynx, and salivary glands. "Nevertheless, the role of CDK19 in the progression and aggressiveness of head and neck squamous cell carcinoma (HNSCC) remains unclear." (PMID 32752128, 2020). "So far, little is known about CDK19’s role in head and neck squamous cell carcinoma (HNSCC) progression, its link to STAT1 activity, and related immune modulation." (PMID 32752128, 2020).
hepatocellular carcinoma (2 papers, 2020 to 2021). A malignant tumor that arises from hepatocytes. "In this study, we utilized public databases and wet-bench hepatic cell line experiments to elucidate the potential roles of CDK19 in hepatocellular cancer (HCC)." (PMID 34649520, 2021). "Here, we show that expression of CDK8, but not CDK19, is increased during dengue virus infection in Huh7 human hepatocellular carcinoma cells, although both are required for efficient viral replication." (PMID 32560467, 2020).
Intellectual disability (2 papers, 2024). "Patients harboring missense mutations in either CDK8 or CDK19 present with a range of clinical features, including neurodevelopmental defects, variable intellectual disability, hypotonia, and facial dysmorphology." (PMID 38637532, 2024). "Most patients with CDK19 pathogenic variants exhibit epilepsy, including infantile spasms, hypotonia, ataxia, developmental delay/severe intellectual disability, central nervous system (CNS) changes on MRI (brain atrophy, delayed myelination), and craniofacial dysmorphisms." (PMID 38637532, 2024).
lung carcinoma (2 papers, 2022). "In the present research, our team added the oncogene CDK19 to the list of miR-205-5p genetic targets in lung cancer cells." (PMID 35627232, 2022). "The results of the dual-luciferase reporter assay, RNA immunoprecipitation, and pull-down assays indicated that hsa_circ_0006692 sponged miR-205-5p, which targeted CDK19 and facilitated the malignant behaviors of lung cancer cells." (PMID 35627232, 2022). "Collectively, these results illustrate that hsa_circ_0006692 is vital for the progress of lung cancer through the hsa_circ_0006692/miR-205-5p/CDK19 axis." (PMID 35627232, 2022). "To further evaluate the interactions of hsa_circ_0006692/hsa-miR-205-5p/CDK19 in lung cancer cells, we carried out a dual-luciferase report assay." (PMID 35627232, 2022). "The impact of hsa_circ_0006692 KD (KnockDown) on promoting cellular proliferative, migratory, and invasive abilities in lung cancer cells could be reversed by the co-transfection of CDK19 OE (Over-Expression)." (PMID 35627232, 2022). "This study revealed that hsa_circ_0006692 promoted NSCLC progression via enhancing cell growth, invasion, and metastasis through sponging mir-205-5p, up-regulating the downstream oncogene CDK19 and modulating EMT of lung cancer cells." (PMID 35627232, 2022). "It was determined that the miRNA expression of genes CDK19, SAMD8, TBL1XR1, and TRPS1 were significantly upregulated in the LUSC dataset between lung cancer patients and controls." (PMID 35885958, 2022).
metastatic prostate carcinoma (2 papers, 2020 to 2023). A carcinoma that arises from the prostate gland and has spread to other anatomic sites. "Further mechanism research revealed that NEAT1-1 could interact with cyclin L1 (CCNL1) through its #4 m6A and acted as a bridge between CCNL1 and cyclin dependent kinase 19 (CDK19) to form a stable complex, which may be specific in in bone metastatic prostate cancer." (PMID 37069649, 2023).
pancreatic cancer (2 papers, 2016 to 2023). "Pbk, Fastk, Cdk19, Adck5, Trim28, and Pfkp may be the regulatory genes for CD73 in pancreatic cancer." (PMID 37835536, 2023). "Pbk, Fastk, Cdk19, Adck5, Trim28, and Pfkp are the genes that may regulate CD73 in pancreatic cancer." (PMID 37835536, 2023).
sarcoma (2 papers, 2013 to 2019). A usually aggressive malignant neoplasm of the soft tissue or bone. "A major genetic network contains known cancer-related or pro-proliferating genes, including CDC25A, CDK19, FUS (fused in sarcoma), TLE3, and ILF3 (interleukin enhancer binding factor 3) was formed." (PMID 24160375, 2013).
triple-negative breast carcinoma (2 papers, 2015 to 2019). An invasive breast carcinoma which is negative for expression of estrogen receptor (ER), progesterone receptor (PR), and human epidermal growth factor receptor 2 (HER2). "CDK19 is a regulator of triple-negative breast cancer (TNBC) showing a role in tumor initiation, proliferation, and metastases." (PMID 31527453, 2019).
autoimmune disease (1 paper, 2019). A disorder resulting from loss of function or tissue destruction of an organ or multiple organs, arising from humoral or cellular immune responses of the individual to their own tissue constituents. "In addition, investigating the role of Cdk8/Cdk19 inhibition on other autoimmune diseases such as graft-vs.-host disease, SLE, and rheumatoid arthritis (RA) will further confirm the function of Cdk8/Cdk19 in adaptive immunity regulation and diversify its application in the field of autoimmunity." (PMID 31552016, 2019).
Autoimmunity (1 paper, 2019). The occurrence of an immune reaction against the organism's own cells or tissues. "To investigate whether Cdk8/Cdk19 inhibition promoted Treg cells were functionally competent to suppress autoimmunity in vivo, we analyzed the inhibitory effect of CCT251921 in EAE model." (PMID 31552016, 2019).
bladder cancer (1 paper, 2016). "Certain MEDs were found to be both over- and underexpressed in the same cancer entity [e.g. MED28 in bladder cancer (both 26%, n = 28/109); CDK19 in kidney cancer (overexpression 66%, n = 33/50; underexpression 32%, n = 16/50)]." (PMID 27050271, 2016). "By taking a closer look at the transcriptome analysis it becomes apparent that several MEDs are found to be both over- and underexpressed dependent on the cancer entity (e.g. MED28 in bladder cancer, CDK19 in kidney cancer)." (PMID 27050271, 2016).
bone cancer (1 paper, 2021). A primary or metastatic malignant neoplasm affecting the bone or articular cartilage. "The lncRNA NEAT1 acts as a bridge between CYCLINL1 and CDK19 to promote Pol II ser2 phosphorylation, which might represent a new target for the treatment and diagnosis of bone cancer metastasis." (PMID 34777473, 2021).
Cognitive impairment (1 paper, 2023). Abnormal cognition is characterized by deficits in thinking, reasoning, or remembering. "Seven differentially expressed autoantibodies were recognised as cognitive impairment-related, including HSPD1, CDK19, TKT, BRSK2, NRAS, LMNA, and CAMK2A." (PMID 38107644, 2023).
coronary artery diseases (1 paper, 2023). "Recent studies also found dysregulated CDK19 to be associated with coronary artery diseases." (PMID 37476628, 2023).
cystic fibrosis (1 paper, 2023). Autosomal recessive disorder caused by pathogenic variants in the CFTR gene (cystic fibrosis transmembrane conductance regulator), which encodes a chloride and bicarbonate channel expressed in epithelial cells, and follow the diagnosis criteria. "Identifying the mechanisms by which CDK8 and CDK19 affect expression of genes in the CFTR pathway may improve understanding the pathophysiology of cystic fibrosis, but will require further studies." (PMID 36545778, 2023). "Whether or not CDK8 or CDK19 are implicated in the pathogenesis of cystic fibrosis also remains an open question." (PMID 36545778, 2023).
developmental delay (1 paper, 2024). "In contrast, in humans, variants in CDK19 act as dominant negative variants and cause developmental delay, infantile spams, hypotonia, and intellectual disability." (PMID 38637532, 2024). "The human CDK19 patients show some similar but milder phenotypes, including developmental delay, seizure, and hypotonia, suggesting that the function of DNM1L is not fully dependent on Pink1 and CDK19." (PMID 38637532, 2024).
epilepsy (1 paper, 2023). A brain disorder characterized by episodes of abnormally increased neuronal discharge resulting in transient episodes of sensory or motor neurological dysfunction, or psychic dysfunction. "Trio-based WES has been successful in defining the most likely epilepsy-implicated loci and screening out candidate genes, such as UNC13B, CELSR3, and CDK19 in numerous studies." (PMID 37152436, 2023).
experimental autoimmune encephalomyelitis (1 paper, 2019). An autoimmune demyelinating disease of the central nervous system that is produced experimentally in animals by the injection of homogenized brain or spinal cord in Freund's adjuvant. "Importantly, treatment with Cdk8/Cdk19 inhibitor CCT251921 significantly increased Treg population and ameliorated autoimmune symptoms in an experimental autoimmune encephalomyelitis (EAE) model." (PMID 31552016, 2019).
HIV-1 infection (1 paper, 2023). The type species of lentivirus and the etiologic agent of acquired immunodeficiency syndrome (AIDS). "Relating to this, we note that it was previously reported that knockdown of CDK8 and/or CDK19 does not affect HIV-1 infection in HeLa cells, where dCA has an inhibitory effect." (PMID 37671866, 2023).
lymph node metastases (1 paper, 2020). "In the next step, we compared CDK19 expression of PTs with and without LR to CDK19 expression of LRs, lymph node metastases, and distant metastases." (PMID 32752128, 2020).
lymphoma (1 paper, 2016). A malignant (clonal) proliferation of B- lymphocytes or T- lymphocytes which involves the lymph nodes, bone marrow and/or extranodal sites. "Lymphoma was found as the only tumor entity to solely show underexpression of its Mediator subunits (most strongly MED28, MED14, MED13, CDK19, all with a frequency of 100%, n = 11/11)." (PMID 27050271, 2016).
melanoma (1 paper, 2021). A malignant, usually aggressive tumor composed of atypical, neoplastic melanocytes. "The function of Cdk8 and the partially redundant Cdk19 protein kinase in humans are of considerable interest because a significant proportion of cancers may have alterations in their activity, particularly of melanoma and colorectal origin." (PMID 34849833, 2021).
metastatic disease (1 paper, 2020). "CDK19 expression in PTs developing DM or LM was not significantly different from PTs not developing metastatic disease." (PMID 32752128, 2020).
non-small cell lung carcinoma (1 paper, 2022). A group of at least three distinct histological types of lung cancer, including non-small cell squamous cell carcinoma, adenocarcinoma, and large cell carcinoma. "Nevertheless, the regulation and function of hsa_circ_0006692 and its interactions with miR-205-5p and CDK19 in the development of non-small-cell lung cancer (NSCLC) were un-explored." (PMID 35627232, 2022).
parasitic infections (1 paper, 2023). "Interestingly, secretory lineage hyperplasia occurs upon parasitic infections and is mediated by pro‐inflammatory cytokines, while CDK8 and CDK19 potentiate NFκB‐mediated pro‐inflammatory transcription and limit production of anti‐inflammatory cytokines." (PMID 36545778, 2023).
Parkinsonism (1 paper, 2024). Characteristic neurologic anomaly resulting from degeneration of dopamine-generating cells in the substantia nigra, a region of the midbrain, characterized clinically by shaking, rigidity, slowness of movement and difficulty with walking and gait. "Here, the authors examine Drosophila Cdk8/CDK19 function in mitochondrial fission and uncover a role phosphorylating Drp1 in the cytoplasm and show overexpression suppresses a Parkinson’s disease model." (PMID 38637532, 2024).
prostate adenocarcinoma (1 paper, 2024). "Elevated CDK19 expression was associated with those prostate adenocarcinoma cell lines that express AR at a high level." (PMID 38546787, 2024).
uterine cancer (1 paper, 2019). Primary or metastatic malignant neoplasm involving the uterine corpus and/or the cervix. "On the other hand, uterine cancers were unique in showing a high frequency of point mutations in CDK8/CDK19/CCNC." (PMID 31382571, 2019). "The impact of the CDK8/CDK19/CCNC mutations found in uterine cancers is unknown, but we note that uterine cancers were also one of the types that showed correlations between the expression of CDK8 and CDK19 and shorter survival." (PMID 31382571, 2019). "Among other cancer types with relatively frequent alterations of CDK8, CDK19, or CCNC, we note cancers of the uterus, where mutations of these genes were found more frequently than in the other cancer types; most of these were missense mutations of unknown significance." (PMID 31382571, 2019).